CXCL16 (C-X-C motif chemokine ligand 16)
Diseases named in the same sentence as CXCL16 in open-access papers (continued):
Sharing a sentence is not in itself a finding about the gene and the disease.
lung carcinoma (24 papers, 2014 to 2025). "Discrepancies between the two lung cancer subtypes are attributed to the variant expression of MMPs following CXCL16 stimulation." (PMID 39512767, 2024). "Previous report has indicated that CXCL16/CXCR6 signaling pathway associates with the development of lung cancer." (PMID 31379980, 2019). "CXCL16 is overexpressed in patients with lung cancer, while its expression is predominantly decreased after chemotherapy and VEGF-targeted therapy, which is associated with better response rates." (PMID 38698468, 2024). "For instance, in lung cancer cell metastasis, CXCL16 can exist as membrane-bound CXCL16 and soluble CXCL16." (PMID 39512767, 2024). "The CXCR6‒CXCL16 axis is involved in several pathological processes, and they are overexpressed in different types of cancer, such as prostate, breast, ovary, and lung cancer, as well as schwannomas, promoting invasion and metastasis." (PMID 33920834, 2021). "CXCL16 is produced by the cancer cells of tumors such as glioblastoma multiforme, lung cancer, lymphoma, and nasopharyngeal carcinoma." (PMID 33800554, 2021). "CXCL16 also has an osteoclastogenic activity which is necessary for the formation of bone metastasis by lung cancer A549M1 cells." (PMID 33800554, 2021). "CXCL16 expression also depends on receptors, e.g., complement C5a receptor 1 (C5aR1) in lung cancer cells." (PMID 33800554, 2021). "CXCL16 has been described this year to play an important role in C5aR1 signaling related osteoclastogenic activity in lung cancer cells, impairing osseous colonization." (PMID 31897234, 2020). "In this article, serum CXCL16 levels in lung cancer patients and expression of CXCL16 in lung cancer samples were examined to evaluate the clinical implications for NSCLC patients." (PMID 32163231, 2020). "Accordingly, a recent study described high CXCL16 expression in lung cancer cells as a positive prognostic factor." (PMID 29285224, 2017). "Three kinds of lung cancer cell lines all secreted CXCL16 spontaneously almost at a constant rate, but there was a slight difference in the concentration of CXCL16 in the culture medium." (PMID 24897301, 2014). "The results clearly demonstrated that not only CXCR6 and CXCR4 (30/33) but also CXCL12 and CXCL16 (19/33) were coexpressed in both human primary lung caner tissues and lung cancer cell lines." (PMID 24897301, 2014). "In ovarian, thyroid, and lung cancers CXCL16 promotes tumor progression." (PMID 37055410, 2023). "Evidently, ORFV NA1/11 infection of lung cancer cells induced oncolysis of tumor cells to release danger-associated molecular patterns, and promoted dendritic cell maturation, and CD8 T cell infiltration in the tumors by enhancing CXCL16 secretion." (PMID 35959371, 2022). "Therefore, ORFV NA1/11 infection significantly elevated CXCL16 secretion by lung cancer cells, promoted DCs activation, and recruited more CD8 T cells to enhance antitumor T cell responses." (PMID 35959371, 2022). "It was shown that protein expression levels of chemokine CXCL16 which regulates inflammation, growth hormone receptor (GHR) and PRL were elevated in lung tumor tissue, which was associated with decreased survival of patients with lung cancer." (PMID 34487971, 2021). "The CXCR6‒CXCL16 axis is involved in several pathological processes, and its overexpression has been detected in different types of cancer, such as prostate, breast, ovary, and lung cancer, along with schwannomas, in which it promotes invasion and metastasis." (PMID 33920834, 2021). "Moreover, overexpression of CXCL16 has accelerated the proliferation and metastasis of lung cancer cells." (PMID 31379980, 2019). "However, both exogenous CXCL16 and CM (conditioned medium from A549, 95D or H292) significantly improved the in vitro viability and invasion of three lung cancer cell lines." (PMID 24897301, 2014).
lung carcinoma (continued). "Specific brown-coloured staining for CXCR6 and CXCL16 in the cytoplasm and membrane could be clearly observed in the primary lung cancer cells, but the positive expression rate and staining intensity of CXCR6 was stronger than that of CXCL16." (PMID 24897301, 2014). "The promoting effect of CXCL16 on invasion of three lung cancer cell lines was highly consistent." (PMID 24897301, 2014). "However, blocking CXCL16-CXCR6 axis by CXCL16 neutralizing antibody or CXCR6 protein down-regulation only partially blocked the increased invasion of lung cancer cell lines induced by the CM (compared with the control, P<0.01)." (PMID 24897301, 2014). "Recently, ORFV infection of lung cancer cells induced tumor cell oncolysis to release risk-associated molecular patterns and promoted dendritic cell maturation and CD8+ T cell infiltration in tumors by enhancing C-X-C motif chemokine ligand 16 (CXCL16) secretion." (PMID 37009515, 2023). "However, little is known about the effect of serum CXCL16 levels in lung cancer patients." (PMID 32163231, 2020). "Moreover, C5aR1 also promotes bone metastasis of lung cancer by CXCL16-mediated effects." (PMID 30686982, 2018). "Thus, it is reasonable to speculate that lung cancer cells could regulate their own biological functions in a self-regulation manner through the coexpression of CXCL16 and CXCR6." (PMID 24897301, 2014). "However, exogenous CXCL16 and CM effectively promoted the in vitro invasiveness of lung cancer cell lines, and the induced invasive ability could be obviously blocked by CXCL16 neutralizing antibody or CXCR6 gene down-regulation." (PMID 24897301, 2014). "However, the role of CXCL16 in lung cancer immunotherapy remains unclear." (PMID 38698468, 2024). "However, the role of CXCL16 in anti-PD-1/PD-L1 therapy for lung cancer remains unknown." (PMID 38698468, 2024). "Lung cancer cells also highly express CXCL16/CXCR6, which promote lung cancer cell migration and invasion in vitro and bone metastasis in vivo." (PMID 37025604, 2023). "Our data indicated that ORFV NA1/11 infection triggered the apoptosis of lung cancer cells and inhibited the growth of implanted lung tumors in mice by enhanced release of HMGB1, ATP and CXCL16 secretion to promote DCs activation and recruit CD8 T cells." (PMID 35959371, 2022). "Differences in localization between CXCL16 and VEGF‐A expression were clarified in the samples identified in lung cancer tissue array." (PMID 32163231, 2020). "CXCL16 and VEGF‐A expressions in lung cancer tissue were also evaluated by immunohistochemical tests." (PMID 32163231, 2020). "We assessed the expression of CXCL16 and VEGF‐A and conducted analysis using lung cancer tissue microarray (US Biomax, Inc., Rockville, MD, USA)." (PMID 32163231, 2020). "Fisher's exact tests were conducted for the comparison of CXCL16 and VEGF expression in lung cancer tissue array and the comparison of the response rate between the low and high CXCL16 groups." (PMID 32163231, 2020). "Immunohistochemical analysis for the expression of CXCL16 and VEGF‐A was performed using lung cancer tissue microarray (US Biomax, Inc., Rockville, MD, USA)." (PMID 32163231, 2020). "We also found that the expression of IL-6, CXCL16, or IGFBP-4 significantly predicted the poor overall survival in patients with lung cancer." (PMID 27095254, 2016). "We present the first study on the prognostic impact of the chemokines CXCL16 and CXCR6 in lung cancer." (PMID 26021984, 2015). "It was demonstrated that similar to CXCL12 and CXCR4, CXCL16 and CXCR6 were also coexpressed in human primary lung cancer tissues." (PMID 24897301, 2014). "In the present study, the expression of CXCL16 and CXCR6 in human lung cancer tissues and lung cancer cell lines, A549, H292 and 95D, was determined by immunohistochemistry and immunocytochemistry respectively." (PMID 24897301, 2014).
lung carcinoma (continued). "After confirming the functional existence of CXCL16 and CXCR6 protein in A549, 95D and H292 cells by ELSA and flow cytometry analysis, we further explored the significance of CXCL16-CXCR6 axis in the biological functions of lung cancer cell lines in vitro." (PMID 24897301, 2014). "Expression intensity of CXCL16/CXCR6 and CXCL12/CXCR4 protein in human lung cancer tissues." (PMID 24897301, 2014). "We found that ORFV NA1/11 infection enhanced CXCL16 expression and secretion in lung cancer cells and co-culture of T cells from WT mice, but not from CXCR6-/- mice, with ORFV NA1/11-infected lung cancer cells promoted the migration of CD8 T cells in a transwell experimental system." (PMID 35959371, 2022). "However, no studies have examined the impact by CXCR6 and CXCL16 on lung cancer survival." (PMID 26021984, 2015).
COVID-19 (22 papers, 2020 to 2026). A disease caused by infection with severe acute respiratory syndrome coronavirus 2. "The genotype of CXCL16 rs8071286 locus significantly correlates with the serum levels of corresponding cytokines in critical cases of COVID-19." (PMID 40050290, 2025). "Recent studies on COVID-19 patients have demonstrated that the expression of CXCL16 is upregulated during the inflammatory response and its level is higher in severe disease compared to healthy controls and individuals with a mild infection." (PMID 39062835, 2024). "Recent studies revealed that the CXCR6/CXCL16 axis plays an important role in severe COVID-19 immunopathogenesis." (PMID 37762093, 2023). "In patients with respiratory diseases, the CXCR6/CXCL16 axis is known to attract T cells to the lungs and this mechanism appears to play a role in the COVID-19 immunopathogenesis as well." (PMID 37762093, 2023). "ScRNA-seq analysis of BALF also revealed increased expression of CXCL9, CXCL10, CXCL11, and CXCL16 in all tested COVID-19 patients." (PMID 33335518, 2020). "The MCODE plugin in Metascape was used to determine important modules and related hub genes in the constructed PPI network, and chemokines such as CCR1, CCL19, CXCL10, and CXCL16 were identified to present the most obvious changes in COVID-19 disease progression." (PMID 33195212, 2020). "High levels of these molecules, detected after macrophage treatment with VLPs (TNFα, IL-1β, CCL8, CXCL8, CXCL9, CXCL16, CXCL1, and CXCL2), were shown to correlate with severe COVID-19 in other studies." (PMID 38664730, 2024). "Some COVID-19 convalescent plasma indicated high levels of IgGs to certain chemokines (for example, CCL8, CXCL13 and CXCL16) compared with healthy controls." (PMID 36879067, 2023). "A higher expression of chemokines (CXCL1, CXCL2, CXCL3, CXCL8 and CXCL16) were also found in the CD4+ TCM and Classical Monocytes in the COVID-19 patients." (PMID 36532041, 2022). "Comparison of severe and mild Symptomatic COVID-19 cases revealed an upregulation of CD177, the neutrophil marker, CXCL16, MAPKMAPK2 and IRF2BP2 with downregulation of ISGs; IFIT, IFIT3, OAS1, OAS2, LY6E and MX1 in severe cases." (PMID 34824360, 2021). "For COVID-19, CCL2 recruits neutrophils, monocytes, and macrophages, and CXCL9 and CXCL16 recruit T cells and NK cells to the site of viral infection." (PMID 35002688, 2021). "In COVID-19, men demonstrated lower expression of cytokines with protective effects against viral infection, including CCL2, CCL3, CCL4 and CXCL16, than women." (PMID 32974111, 2020). "Interestingly, a recent study reported that 12 months after infection, patients with mild COVID-19 had higher autoantibody levels to cytokines such as CCL21, CXCL13, and CXCL16, compared to long COVID-19 patients." (PMID 38491326, 2024). "Moreover, patients with severe COVID-19 have fewer lung-resident memory CD8+ T cells with lower expression of CXCR6, and their lung macrophages produced less CXCL16 compared to moderately ill patients." (PMID 37762093, 2023). "Changes in chemokine levels in peripheral blood of COVID-19 and influenza patients have been addressed by multiple studies, in particular CXCL9, CXCL10, CXCL11, CXCL16, CCL2, and CCL5 were altered in patients as compared to controls, and levels correlated to disease severity." (PMID 35371005, 2022).
colon carcinoma (19 papers, 2009 to 2025). "Also, a higher expression of CXCL16 in regional lymph nodes is associated with poorer overall survival for colon cancer patients." (PMID 33800554, 2021). "Correlations between LGR6 mRNA expression levels and expression levels of LGR4, LGR5, CEA and CXCL16 mRNAs in lymph nodes of colon cancer patients." (PMID 38715790, 2024). "Enhanced CXCL16 expression in colon cancer has been shown to correlate with increased T-cell infiltration and better prognosis in patients with cancer." (PMID 37478172, 2023). "In colon carcinoma, for example, it has been shown that colorectal tumor cells manipulate healthy neighboring cells via CXCL16 in exosomes, and can thus increasingly metastasize." (PMID 36078040, 2022). "MiR-873-5p has been proved as a tumor suppressor in papillary thyroid cancer by targeting CXCL16 and in colon cancer via the inhibition of TUSC3." (PMID 35241028, 2022). "In the Hong colorectal dataset, CXCL16 was upregulated in colon carcinoma (fold change = 2.636, P = 2.08E-18)." (PMID 34233297, 2021). "Strong expression of the CXCL16 protein in primary colon tumor tissue was reported to be correlated to a good prognosis." (PMID 32812032, 2020). "CXCL14 and CXCL16 mRNA levels and protein expression were significantly higher in colon cancer primary tumors compared to apparently normal colon tissue." (PMID 31752131, 2019). "In conclusion, high expression of CXCL16 mRNA in regional lymph nodes of colon cancer patients is a sign of a poor prognosis." (PMID 31752131, 2019). "The median expression levels of CXCL14 and CXCL16 mRNA in primary colon tumors (n = 32) were 13 and five times higher than the median expression levels in normal colon tissue (n = 30), respectively." (PMID 31752131, 2019). "CXCL16 mRNA was expressed in 5/5 colon cancer cell lines while CXCL14 was expressed significantly in only one." (PMID 31752131, 2019). "This assumption is further supported by other studies investigating CXCL16 in solid tumours, including non-small cell lung cancer and colon cancer." (PMID 29285224, 2017). "Circulating MAIT cells exhibited high levels of CCR6 and CXCR6, and their corresponding chemokines, such as CCL20 and CXCL16, were strongly expressed in colon cancer tissues." (PMID 27517754, 2016). "In the MC38 colon cancer model, we detected higher levels of CXCL16 upon c-Myb expression." (PMID 37478172, 2023). "Recently, we discovered that chemokines CXCL17 and CXCL16 are ectopically expressed in colon cancer (CC) and could serve as biomarkers for poor prognosis." (PMID 35008827, 2021). "We investigated the expression of CXCL14 and CXCL16 in colon cancer." (PMID 31752131, 2019). "Kaplan-Meier analysis revealed that colon cancer patients with lymph nodes expressing high or very high levels (7.2 and 11.4 copies/18S rRNA unit, respectively) of CXCL16 mRNA had a decreased mean survival time of 30 and 46 months at the 12-year follow-up (P = 0.04, P = 0.005, respectively)." (PMID 31752131, 2019). "Correlations between levels of PRSS3 and PRSS22 mRNAs and CEA, CXCL16, CXCL17, GPR35 V2/3, LGR5, LGR6 and KLK6 mRNA levels in lymph nodes of colon cancer patients." (PMID 40909962, 2025). "The aim was to investigate whether the stem cell marker LGR6 has prognostic value in colon cancer, alone or in combination with the prognostic biomarkers CEA and CXCL16." (PMID 38715790, 2024). "Furthermore, we found that colon cancer tissues exhibited higher expressions of CCL20 and CXCL16, but similar expressions of CCL21 and CXCL10 as compared with unaffected tissue, which is in line with previous studies." (PMID 27517754, 2016). "We previously studied mRNA biomarkers that correlated with poor prognosis in colon cancer (CC) patients, such as leucine-rich repeat-containing G protein-coupled receptors 5 and 6 (LGR5 and LGR6), as well as C-X-C motif chemokine ligands 16 and 17 (CXCL16 and CXCL17)." (PMID 40909962, 2025).
colon carcinoma (continued). "CXCL16, but not CXCL14, mRNA levels were significantly higher in hematoxylin and eosin positive (H&E(+)) compared to H&E(−) colon cancer lymph nodes or control nodes (P < 0.0001)." (PMID 31752131, 2019).